TMEM190 (transmembrane protein 190)
Synonyms: MDAC1
Tractability: Antibody: UniProt predicts a signal peptide or a membrane-spanning region.
Gene: Protein-coding gene on chromosome 19 (55,376,816 to 55,378,246, forward strand). Ensembl gene ENSG00000160472.
Subcellular location: Membrane
Gene Ontology:
Molecular function: protein binding; identical protein binding
Biological process: hematopoietic progenitor cell differentiation
Cellular component: nucleus; inner acrosomal membrane; membrane
Genetic constraint (gnomAD): Loss-of-function variants: 17 observed, 18.03 expected, observed/expected ratio (o/e) 0.94, 90% interval 0.64 to 1.41. The upper end of that interval is the gene's LOEUF score, 1.41, which puts it in group 5 of 6, group 1 being the genes least tolerant of losing a copy. Missense variants: 246 observed, 239.98 expected, observed/expected ratio (o/e) 1.03, 90% interval 0.92 to 1.14. Synonymous variants: 101 observed, 100.45 expected, observed/expected ratio (o/e) 1.01, 90% interval 0.86 to 1.19.
Homologues: Orthologues: chimpanzee TMEM190 (99% identical), macaque TMEM190 (86% identical), pig TMEM190 (79% identical), dog TMEM190 (78% identical), guinea pig TMEM190 (73% identical), rat Tmem190 (66% identical), mouse Tmem190 (64% identical).
Diseases named in the same sentence as TMEM190 in open-access papers:
TMEM190 is named in the same sentence as 1 disease in open-access papers, as found by Europe PMC text mining. Sharing a sentence is not in itself a finding about the gene and the disease. The quoted sentences say what the papers report.
infertile (1 paper, 2021). "However, co-immunoprecipitation experiments showed that TMEM190 and IZUMO1 have no functional interaction; however, the deletion of TMEM190 produces infertile mice." (PMID 33466297, 2021).